PSG3 (pregnancy specific beta-1-glycoprotein 3)
Tractability: Antibody: UniProt places it where antibodies can reach, with high confidence; UniProt predicts a signal peptide or a membrane-spanning region; its Gene Ontology location is reachable by antibodies, with medium confidence.
Gene: Protein-coding gene on chromosome 19 (42,721,638 to 42,740,481, reverse strand). Ensembl gene ENSG00000221826.
Subcellular location: Secreted
Pathways (Reactome):
Hemostasis: Cell surface interactions at the vascular wall
Gene Ontology:
Biological process: defense response; female pregnancy
Cellular component: extracellular region
Genetic constraint (gnomAD): Loss-of-function variants: 61 observed, 46.66 expected, observed/expected ratio (o/e) 1.31, 90% interval 1.06 to 1.62. The synonymous counts are far from expectation, so gnomAD's model fits this gene poorly and the ratio says little. Missense variants: 756 observed, 519.88 expected, observed/expected ratio (o/e) 1.45, 90% interval 1.37 to 1.54. Synonymous variants: 263 observed, 196.84 expected, observed/expected ratio (o/e) 1.34, 90% interval 1.21 to 1.48.
Homologues: Paralogues in human: PSG1 (89% identical), PSG8 (89% identical), PSG7 (88% identical), PSG6 (88% identical), PSG4 (87% identical), PSG9 (85% identical), PSG5 (70% identical), PSG11 (66% identical), PSG2 (66% identical), CEACAM1 (40% identical), CEACAM5 (37% identical), CEACAM8 (36% identical), and 12 more.
Diseases named in the same sentence as PSG3 in open-access papers:
PSG3 is named in the same sentence as 8 diseases in open-access papers, as found by Europe PMC text mining. Sharing a sentence is not in itself a finding about the gene and the disease. The quoted sentences say what the papers report.
preeclampsia (3 papers, 2014 to 2024). Preeclampsia is a hypertensive disorder of pregnancy that is characterized by new-onset hypertension with proteinuria presenting after 20 weeks of gestation, and depending on mild or severe forms may initially present with severe headache, visual disturbances, and hyperreflexia. "Higher PSG-3 levels are reported in preeclampsia, another gestational disease associated with increased insulin resistance." (PMID 38396626, 2024).
kidney cancer (1 paper, 2025). Primary or metastatic malignant neoplasm involving the kidney. "The signature of PSG3, PSG7, and PSG8 was also found to show a statistically significant survival difference (P = .0138) between the PSG+ and PSG− groups in uterine cancer and borderline significance (P = .0746) in female kidney cancer patients." (PMID 40257008, 2025).
cancer (1 paper, 2025). A tumor composed of atypical neoplastic, often pleomorphic cells that invade other tissues. "We then asked if this pattern (a statistically significant alteration of the ‘KRAS Signaling Down’ pathway between the PSG+ and PSG− groups in female LUAD patients grouped by the signature of PSG3, PSG7, and PSG8) is present in other TCGA cancer datasets." (PMID 40257008, 2025). "The signature of PSG3, PSG7, and PSG8 was further assessed for female patients in other TCGA cancer datasets." (PMID 40257008, 2025).
tumor (1 paper, 2025). "The PSG3 gene had the highest expression level in both male and female tumor samples whereas PSG2, PSG7, and PSG11 had relatively lower expression levels." (PMID 40257008, 2025). "Note that a tumor sample in which PSG3, PSG7, and PSG8 had no expression was defined as PSG− and otherwise was defined as PSG+." (PMID 40257008, 2025).
PSG3 also shares sentences with these, for which no sentence is quoted: Insulin resistance (1 paper); Miscarriage (1); Onset (1); uterine cancer (1).